CD4 (CD4 molecule)
Diseases named in the same sentence as CD4 in open-access papers (continued):
Sharing a sentence is not in itself a finding about the gene and the disease.
Immunodeficiency (continued). "Thus of two elements that largely govern HIV disease, CD4+ cell depletion leading to immunodeficiency and viral expression and response by macrophages leading to brain disease, only the latter is well preserved in EcoHIV infection of mice." (PMID 29879225, 2018). "At baseline in this study, all HISs were cART-naïve with detectable plasma viral loads (median 4.68lg10 copies/ml, IQR 4.18–5.12lg10 copies/ml), and most patients exhibited moderate immunodeficiency (median CD4+ T cell count: 331 cells/mm3, IQR: 247–429 cells/mm3)." (PMID 29934497, 2018). "However, previous studies suggest that B-cell activation markers (e.g., sCD27, sCD30) and immunodeficiency markers (e.g., low CD4 and low CD4:CD8 ratio) represent different classes of early detection markers, linked to NHL through distinct mechanisms." (PMID 30315476, 2018). "The fundamental finding of our work is that EcoHIV infection causes NCI but not CD4+ T cell depletion or immunodeficiency in mice, separating at least part of the causes of these two HIV disease manifestations." (PMID 29879225, 2018). "The higher mortality in the current study may relate to the fact that more than two-thirds (70.0%) of participants had CD4 counts or percentages below the threshold for severe immunodeficiency at the time of ART initiation." (PMID 29482600, 2018). "Finally, we only included a few HIV-infected individuals with severe immunodeficiency (CD4+ T-cell count < 200 cells/μL or ART-untreated), due to the exclusion criterion of antibiotic use." (PMID 30290791, 2018). "During Time Period 2, patients with IRIS-attributable hospitalizations had more advanced immunodeficiency with 83% having CD4 cell counts less than 200 compared to 36% in those admitted for reasons unrelated to IRIS, although this difference was not statistically significant." (PMID 28469696, 2017). "We, therefore, suggest that the combination of the loss-of-function mutation in CTLA-4 with the gain-of-function mutation in JAK3 directs the differentiation of CD4 T cells into dysfunctional TFH cells supporting the development of lymphadenopathy, hypogammaglobulinemia, and immunodeficiency." (PMID 29375547, 2017). "The study on Anaplasma marginale infection in cattle indicated that the percentages of CD4+ and CD8+ T cells expressing both of PD-1 and LAG-3 were increased during acute phase, suggesting that the PD-1+ LAG-3+ T cells contributes to the immune deficiency observed in this infection." (PMID 28445479, 2017). "Surprisingly, novel therapies, like JAK1/2 inhibitors, showed not only the potency to suppress the enhanced STAT1 phosphorylation in CD4+ T lymphocytes but may also improve clinical outcome in both immunodeficiency and autoimmunity features." (PMID 28348565, 2017). "In this setting of immune dysfunction, an abnormal CD4/CD8 ratio can emerge." (PMID 29095912, 2017). "The CD4/CD8 ratio more accurately describes this overall immune dysfunction and may be a better biomarker for disease progression, response to treatment, morbidity, and mortality for the virally suppressed." (PMID 29095912, 2017). "The increase in CD69 in patients with MHE would indicate a persistent activation of CD4+ T lymphocytes which may contribute to immune dysfunction, to altered patterns of cytokines and of CD4+ T cells differentiation and facilitate tissue infiltration." (PMID 28751644, 2017). "CD4/CD8 ratio is a sensitive indicator of clinical diagnosis to determine immune dysfunction." (PMID 28220870, 2017). "Furthermore, CD4+ T cells derived from local environments exhibit greater immune dysfunction than systemic CD4+ T cells." (PMID 29234685, 2017). "For long, clinical decisions in HIV-infected individuals have been based on the CD4+ T cell counts of such individuals, but questions remain as to how well the peripheral CD4+ T cell count mirrors the true state of the immune dysfunction seen in patients who have been infected with HIV." (PMID 29230423, 2017).
Immunodeficiency (continued). "Lymphocyte typing revealed lowered B-lymphocytes and CD4 T-cells (at average CD4/CD8 ratio, natural killer cells, and cytotoxic cells), pointing to a moderate combined (humoral and cellular) immune deficiency, which is typical for individuals with severe alcoholism." (PMID 27799068, 2016). "A study on mice with curdlan-induced SpA indicated that SpA features could be transferred to mice with severe combined immunodeficiency by using CD4+ T cells." (PMID 27350608, 2016). "Immunodeficiency level at the time of HIV diagnosis had an important weight on healthcare spending: the per capita cost for patients with CD4+cell count <200 mm3 was 2 106€ more than patients with CD4+cell count >500 mm3." (PMID 27829390, 2016). "The increased CD4+/CD8+ ratio (P = 0.024) indicates that CS-C-Q80 could correct the cellular immune disorder, at least partially, by inhibiting CD8+ expansion." (PMID 27721890, 2016). "More than half patients had severe immunodeficiency with CD4 cell count less than <200 cells/mm3." (PMID 25886534, 2015). "In Good’s syndrome, several aspects of immunodeficiency may occur in addition to hypogammaglobulinemia, such as low circulating B lymphocytes, CD4+ T-cell lymphopenia, and inverted CD4+ to CD8+ ratio." (PMID 26303293, 2015). "We then hypothesized that the intensity (i.e. nadir CD4 T-cell percentage) and duration of the immunodeficiency would be inversely related to the restoration of HIV-specific T-cell levels after the treatment-induced suppression of viral replication." (PMID 26650393, 2015). "In addition, CD4+ T cell counts were <500 cells/μl in three of the patients, indicating progression to immunodeficiency." (PMID 26279669, 2015). "In this study, we evaluated ADCC activity in HIV-1-positive individuals who initiated ART at different stages of disease: before seroconversion, at CD4+ T cell counts above 350 cells/μl blood and at CD4+ T cell counts below 350 cells/μl blood (at a relevant immunodeficiency)." (PMID 26696395, 2015). "In the present study, we identified several differences in the phenotypes and properties of CD4+ T cells from young and elderly people that may play a role in the high susceptibility of older individuals to HIV-induced immunodeficiency." (PMID 26452480, 2015). "In healthy individuals older than 65 years, these cells may accumulate to up to 50% of total CD4+ T lymphocytes as in many immune-mediated diseases, immunodeficiency, and specific infectious diseases." (PMID 25834833, 2015). "The reason for this is that HIV-negative patients with underlying disease have more obvious immune deficiency and CD4+ T cell-mediated immune deficiency than patients without underlying disease." (PMID 26573268, 2015). "We believe that the data reviewed here supports that the CD4:CD8 ratio represents a marker of immune dysfunction and may contribute to better patient management." (PMID 26130226, 2015). "These infants, though uninfected, possibly take 2 hits: a relative state of immunodeficiency marked by decreased CD4+ T cell count and decreased placental transfer of protective maternal antibodies, and increased exposure to infectious diseases from sicker parents." (PMID 24885498, 2014). "I saw my first patient with severe immune deficiency in 1979 – a very low CD4 count had been noted, but it was not until the first reports of an epidemic occurred in 1981 that the correct diagnosis was made." (PMID 25393987, 2014). "Idiopathic CD4 lymphopenia constitutes a heterogeneous group of immunodeficiencies with characteristically low CD4+ T-cell counts with largely unknown genetic etiology." (PMID 25205547, 2014). "The patient's constellation of symptoms and normal CD4 T-cell count raised suspicion for IACS from interaction between triamcinolone injection and oral ritonavir therapy which would account for her relative immunodeficiency state despite an adequate CD4 T-cell number." (PMID 24895495, 2014).
Immunodeficiency (continued). "Thus, to suppress the activities of CD4+ effector T cells to given extents has therapeutic effect on immune disorders." (PMID 25533220, 2014). "Adherence to guidelines was poorer in treatment of mild immunodeficiency (200–350 CD4 cells/mm3) which physicians may have considered less urgent than the treatment of more advanced immunodeficiency (CD4<200 cells/mm3)." (PMID 23936509, 2013). "Among the 10 EBV-positive cases, all patients were >50 years old, 2 patients had idiopathic CD4+ T-cell lymphopenia and 1 patient had a history of common variable immunodeficiency, supporting this hypothesis." (PMID 23401819, 2013). "Its role is likely to be as an add-on test within the diagnostic algorithm to permit point-of-care diagnosis and immediate TB treatment among patients with advanced immunodeficiency (CD4 counts <200 cells/μl) following admission to hospital or enrolling in ART clinics." (PMID 24295487, 2013). "In addition, we show that the significant decline in CD4+ T-cell counts, which fell to below or near 200 cells/μl defining immunodeficiency in nearly all subjects, was the result of infection by R5 C-HIV strains that persisted exclusively in 19/21 subjects." (PMID 23824043, 2013). "Finally the number of lymphocytes decreases again; slowly during the latent period and faster during the final stage which is characterized by a notorious immunodeficiency with CD4 counts below 500 CD4/μl3." (PMID 24034560, 2013). "In addition, similar proportions of AAs (13.0%) and others (17.5%) had severe immunodeficiency at baseline (CD4 count < 350 cells/μl)." (PMID 24294218, 2013). "Impaired CD4+ T-lymphocyte response and other forms of immune dysfunction may be responsible for altering the natural history of HPV infection among HIV infected individuals." (PMID 23842471, 2013). "HIV-mediated immune dysfunction may influence CD4+ T cell recovery during suppressive antiretroviral therapy (ART)." (PMID 24391889, 2013). "In agreement with this, in natural Simian Immunodeficiency Virus (SIV) infections in the wild there is no loss of CD4+ T cells or immunodeficiency in infected animals despite high levels of viremia." (PMID 23202514, 2012). "Moreover, as evidenced from this study, two third of the patients were at WHO clinical stage III or IV and half of them had absolute CD4 count below the threshold for severe immunodeficiency at ART initiation." (PMID 23043325, 2012). "The assay only has utility in those with HIV infection and advanced immunodeficiency (CD4 cell counts <200 cells/μL and/or WHO stage 3 or 4 disease) and therefore should not be used to test unselected TB suspects attending medical out-patient clinics or TB clinics." (PMID 22536883, 2012). "About half of them (52.6%) had absolute CD4 count below the threshold for severe immunodeficiency." (PMID 23043325, 2012). "Further suggesting a link between lung cancer and HIV-related immunodeficiency, large cohorts of HIV-infected persons have recently reported strong associations between declining CD4+ counts and lung cancer risk." (PMID 22240797, 2012). "Additionally, low haemoglobin level (less than 10gm/dl), absolute CD4 cell count below the threshold for severe immunodeficiency and delayed or regressing developmental milestone at baseline were predictors of mortality." (PMID 23043325, 2012). "The other predictor of mortality was CD4 count below the threshold for severe immunodeficiency." (PMID 23043325, 2012). "Our data suggest that individuals with ICOS deficiency may have progressively worsening defects in their EM CD4 T cell mediated protection, perhaps leading to progressively worse immunodeficiency and recurring infections." (PMID 21364749, 2011). "Patients had advanced immunodeficiency with a median CD4 cell count of 81 cells/μL (IQR, 35-147)." (PMID 21957868, 2011).
Immunodeficiency (continued). "By including HIV-negative immunosuppressed patients in our study, we have further explored whether immune dysfunction in addition to CD4 counts can affect the detection of these polyomaviruses." (PMID 21436884, 2011). "Eighteen percent of 137 children age 1 to 3 years had CD4+ T-lymphocyte percentages ≤30%, the threshold for immunodeficiency in this age group, with 16 meeting the criterion for mild (CD4+ 25% to 30%), 6 for advanced (CD4+ 20% to 24%), and 3 for severe (CD4+ < 20%) immunodeficiency." (PMID 19944455, 2010). "We observed decreased levels of recent thymic emigrants in CD4+ and CD8+ T cells that may underlay the persistent immunodeficiency in CML patients." (PMID 20470401, 2010). "To determine if CMV-specific T cell responses were elevated before the onset of immunodeficiency, we identified those study participants who were antiretroviral-untreated and had at the time of the analysis a peripheral CD4+ T cell count greater than 500 cells/mm3 (n = 146)." (PMID 20126452, 2010). "The CD4+T-lymphocyte percentages in 35% of healthy children under 1 year and 18% of children age 1 to 3 years were below the World Health Organization threshold defining immunodeficiency in HIV-infected children in resource-limited settings." (PMID 19944455, 2010). "Although median and centile values determined in the current study were from healthy HIV-uninfected African children, the relative low CD4+ T-lymphocyte percentages in children under 1 year old meant that 35% of these children met the CD4 criterion for immunodeficiency in HIV-infected children." (PMID 19944455, 2010). "As FOXP3 expression may be affected by the degree of immunodeficiency, we analysed the relationship between the CD4+T cell count and the percentage of CD4+T cells expressing FOXP3." (PMID 20668701, 2010). "Hence it is important to establish the reference ranges for the CD4+ T cell counts in the target population to understand the immune dysfunction." (PMID 21245613, 2010). "Decreased VEGF may reflect greater immune dysfunction due to failure of CD4+ T cell antigen recognition from antigen-presenting cells." (PMID 21253011, 2010). "Hence CD4+ T lymphocyte count is the most important marker of immune dysfunction in HIV disease progression." (PMID 21245613, 2010). "In addition to immunodeficiency, conditional deletion of activated/memory CD4+ T cells by CD134-driven DTA activation also leads to generalized immune activation, which shares many features with HIV infection-associated immune activation." (PMID 19943952, 2009). "Additionally, this subject group had the lowest blood CD4+ T cell counts, indicating a state of increased immunodeficiency." (PMID 19390619, 2009). "However, patients with eye disease had more advanced immunodeficiency as reflected by significantly lower CD4 cell counts and more advanced WHO stage of disease." (PMID 19775470, 2009). "Importantly, the model also shows that highly active antiretroviral therapy (HAART) can inhibit X4 emergence but that monotherapy with CCR5 blockers can accelerate X4 onset and immunodeficiency if X4 infection of memory CD4+ T cells occurs at a high rate." (PMID 19680436, 2009). "Importantly, all subjects in this study had CD4 counts above 200 cells/mm3, so it will be important to evaluate the diagnostic utility of LPA in subjects with more profound HIV-related immunodeficiency." (PMID 19236695, 2009). "A recently published study showed that among TB cases lower CD4 cell counts are associated with a higher likelihood of a positive LAM-ELISA in urine, which would make the assay a promising rapid TB diagnostic tool among patients with advanced immunodeficiency." (PMID 19715562, 2009). "We also examined whether the viral decay rates measured by HTA were correlated with the degree of immunodeficiency by analyzing CD4 counts for each group of subjects." (PMID 19390619, 2009).
Immunodeficiency (continued). "The CSF cellular response may depend in part on the peripheral blood CD4+ T lymphocyte count, despite the advanced level of immunodeficiency observed in these patients, as a positive correlation was found between both variables." (PMID 19906308, 2009). "CD4 count is a standard measure of immunodeficiency in adults infected with HIV to initiate and monitor highly active antiretroviral therapy; however, it may not be feasible in resource poor countries." (PMID 19102769, 2008). "Because lymphopenia is often found in advanced HIV-associated immunodeficiency, a normalized input of PBMC used in ELISPOT assays may partly explain why this assay appears to retain its efficiency among patients with low CD4+ cell counts." (PMID 19343092, 2008). "These events may contribute to the pathogenesis of immune dysfunction and CD4+ T cell losses in chronic infection with the human immunodeficiency virus." (PMID 18382686, 2008). "We focus on the hypothesis that advanced pre-treatment immunodeficiency diminishes the capacity for CD4 cell count recovery during ART as determined by rates of CD4 cell count increase and risk of immunological non-response." (PMID 16551345, 2006). "Furthermore, although we adjusted for CD4 counts to estimate the effect of HIV-1 viremia on cancer risk that was not mediated by immunodeficiency, we did not perform a formal mediation analysis." (PMID 39736138, 2025). "Furthermore, we found among PLWH not on cART that immune deficiency characterized by low CD4+ T-cell count did not seem to influence the incidence of endemic HCoV infection." (PMID 40531922, 2025). "Although the CD4+T cell counts for all five patients were below the limit of detection, the immune conditions of patients P1, P2 and P3 could be classified as immunodeficiency; these conditions may contribute to the persistence and evolution of the virus." (PMID 41304297, 2025). "In PWH, CD4 cell count is one of the most important laboratory measures of immune function; when CD4 cell count drops below a certain level, PWH are at higher risk of immunodeficiency and are more susceptible to infections that can lead to advanced HIV disease (AHD) or death." (PMID 38778273, 2024). "The consistent alterations in LCK-deficient T cells corroborates common clinical, immunological, and molecular manifestations of this rare immunodeficiency including the potential diagnostic hallmark of reduced CD4 expression but absence of autoimmunity until HSCT in one of our patient." (PMID 38112969, 2023). "Thus, an immune response against Pneumocystis β-glucan might occur under conditions of CD4+ T cell-related immunodeficiency via differential CD4+ T cell-dependent regulation of mucosal antibody responses." (PMID 36845149, 2023). "Also, the severity of HIV-induced immune deficiency, as reflected by the CD4 cell count, does not correlate with short-term outcomes in PLHIV admitted for acute respiratory failure, neurological failure, or sepsis." (PMID 37608140, 2023). "In this sense, our tool could greatly interest clinicians in patients with immune dysfunction (CD4+ lymphocyte count < 500 cells/mm3, CD4/CD8 ratio < 0.9, CD8+ lymphocyte count > 1000 cells/mm3), despite virological control of HIV infection with ART, before switching to a 2DR with DTG plus 3TC." (PMID 36769822, 2023). "In addition to the already discussed roles of Th1 and Th17 CD4+ T cells in dry eye and herpetic keratitis, Th2 CD4+ T cells were shown to contribute to corneal epithelial barrier dysfunction in ocular allergy, a Th2-predominant immune disease in which corneal nerves are barely affected." (PMID 37217914, 2023). "In contrast, the infiltration of B naive cells, plasma cells, CD4 memory resting T cells, CD8 T cells, resting NK cells, resting dendritic cells, and monocytes in the high‐risk group was considerably lower than that in the low‐risk group, implying that the high‐risk group had immune deficiency." (PMID 35441810, 2022).